FLT3 (fms related receptor tyrosine kinase 3)
Diseases named in the same sentence as FLT3 in open-access papers (continued):
Sharing a sentence is not in itself a finding about the gene and the disease.
leukemia (continued). "Also, murine leukemia stem cells transduced with FLT3-ITD-coding gene had increased amount of surface PD-L1 after in vitro differentiation into dendritic cells." (PMID 31185600, 2019). "The overexpression of the Fms-like receptor tyrosine kinase-3 (FLT-3) in MLL-r leukemia, which results in the constitutive activation of FLT-3 signaling, could provide an opportunity for therapeutic targeting." (PMID 31671855, 2019). "Gilteritinib significantly reduced the colony-forming capacity of FLT3/ITD-positive leukemia cells." (PMID 30514344, 2018). "Cabozantinib exerts significant cytotoxicity to leukemia cell lines with FLT3/ITD." (PMID 30514344, 2018). "Interestingly, all three AML patients who harbored FLT-3 internal tandem duplication (ITD) mutations, a prognostic marker in AML with poor prognosis, were able to lyse leukemia containing CD3-cell fractions following allogeneic stimulation." (PMID 30323982, 2018). "Using xenotransplantation, they assessed the development of leukaemia upon activation of FLT3." (PMID 28819864, 2018). "To assess whether AC-4–130 could inhibit STAT5 activity in an in vivo leukemia setting, we used a FLT3-ITD–dependent MV4–11 tumor xenograft model." (PMID 29472718, 2018). "Additionally, c-MYC generates repair errors by regulating transcriptional activation and expression of the alternative nonhomologous end-joining pathway resulting in aberrant DNA repair in Flt3-ITD leukemia." (PMID 30420889, 2018). "Importantly, these progenitors are likely to also be key cellular targets for recurrent FLT3 driver mutations in patients with acute B‐cell progenitor and ETP leukaemia." (PMID 30596405, 2018). "Furthermore, ATO combined with sorafenib, a FLT3 TKI, in vivo reduced growth of FLT3/ITD+ leukemia cells in NSG recipients." (PMID 30250637, 2018). "ATO has the potential to improve the efficacy of FLT3 TKIs in the treatment of FLT3/ITD+ leukemia." (PMID 30250637, 2018). "In leukemia cells, FL stimulates auto/paracrine signaling and impedes the efficacy of FLT3 TKIs." (PMID 30250637, 2018). "In vivo FLT3+ leukemia model showed that FLT3L CAR-T could significantly prolong the survival of leukemia beard mice." (PMID 29716633, 2018). "So, the phosphorylation of STAT5, AKT, and ERK1/2 which might be activated by FLT3L in FLT3+ leukemia cells and promote the survival of leukemia cells was further explored." (PMID 29716633, 2018). "In other words, this may be the reason why the FLT3 wild-type leukemia cells were insensitive to FLT3L-based CAR-T cells." (PMID 29716633, 2018). "Some therapeutically-targetable leukemia antigens originate from oncogenesis itself and are leukemia cell-specific, such as the BCR/ABL1 fusion protein in CML and Philadelphia (Ph)+ ALL, PML/RAR-α in acute promyelocytic leukemia, FLT3-ITD and mutated NPM1 in AML and IDH1/2." (PMID 29466292, 2018). "FLT3L CAR-T could interact and eradicate both FLT3+ leukemia cell lines and primary AML cells at the E:T ratio as low as 1:8." (PMID 29716633, 2018). "Here we investigate the feasibility of combining ATO with FLT3 TKIs, with a specific focus on understanding ATO's effect on the degradation of mutant FLT3 protein, as a strategy to increase the efficacy of FLT3 TKIs in the aim to improve the treatment of FLT3/ITD+ leukemia." (PMID 30250637, 2018). "As a result, proliferation and survival of FLT3-WT leukemia cells were promoted." (PMID 29716633, 2018). "We therefore investigated whether high GFI1 expression in the CN-AML FLT3-WT leukaemias corresponds to higher abundance of the FLT3-ITD molecular signature genes." (PMID 28894287, 2017). "Moreover, bortezomib has already shown considerable antileukemic activity, especially in myelomonocytic and FLT3-mutant leukemias." (PMID 28416751, 2017).
leukemia (continued). "Further investigation of the role of FL in normal hematopoiesis might provide clues as to the manner in which FLT3-related leukemias can be treated." (PMID 28538663, 2017). "In addition to previous reports of a leukemia therapy using inhibition of Flt3 trafficking, our study shows that inhibition of mutant receptor trafficking represents a promising strategy for the treatment of cancers." (PMID 28403213, 2017). "AXL signals through many of the same downstream oncogenic pathways as FLT3 so may serve as a bypass mechanism that allows leukemia cells to survive FLT3 inhibition." (PMID 29806049, 2017). "Importantly, our results also suggest that the effects of midostaurin can be potentiated by dual FLT3/SYK suppression or more targeted SYK suppression in the context of midostaurin-resistant leukemia and in FLT3-ITD-expressing primary cells." (PMID 28881711, 2017). "Thus, these discoveries motivate us to consider a combination trial between TQ and inhibitors for KIT and FLT3 signaling in ongoing studies for improving therapeutic outcomes in leukemia." (PMID 28415607, 2017). "As highly activated SYK has been found to occur at a higher frequency in AML patients harboring the ITD mutant than patients expressing wt FLT3, we were interested in exploring the activity of midostaurin against SYK using cell-based models of SYK-driven and SYK- and FLT3-driven leukemia." (PMID 28881711, 2017). "As stromal cell-mediated chemoresistance has proven to be a challenge for TKI-treated leukemia, and TKIs, such as midostaurin, are now in clinical use for mutant FLT3-positive leukemia, it was of interest to explore the clinical and cooperative potential of NOX-A12 in the context of this disease." (PMID 29299123, 2017). "Interestingly, additional SYK suppression potentiated the effects of dual FLT3/SYK inhibitors and targeted FLT3 inhibitors against FLT3-ITD-driven leukemia, both in the absence and presence of activated SYK." (PMID 28881711, 2017). "Recently, single cell analysis demonstrated that not all of the leukemia cells in genomic FLT3-ITD+ patient possess the FLT3-ITD mutation." (PMID 29262547, 2017). "Flt3lig and its receptor (Flt3) also contribute to the pathogenesis of leukemia." (PMID 28408741, 2017). "Even though both FLT3-ITD and FLT3-TKD mutations confer ligand-independent receptor activation, the mechanisms by which they contribute to the development of leukemia might be different." (PMID 28538663, 2017). "Taking these findings together, the leukemias with Flt3-activating mutations, which include AML and ALL, might well have arisen from the Flt3+ primitive stem cell compartment of the bone marrow." (PMID 28498310, 2017). "This could be of particular interest for potential therapeutic applications in leukemias with wild-type FLT3 over-expression." (PMID 28538663, 2017). "This could be beneficial since Flt-3 is known to regulate PIM kinase activity in leukemia, albeit the relatively high IC50 towards Flt-3 of 0.134 μM12 would require further optimization." (PMID 29042609, 2017). "This may serve as an attractive STAT5 inhibitor not only for FLT3/ITD+ AML but more broadly for other leukemia and myeloproliferative neoplasms with constitutive STAT5 activation to be tested in future studies." (PMID 28667329, 2017). "It is speculated that FLT3/ITD mutation could make the LSCs more capable of expanding in the environment and development of leukemia." (PMID 27465508, 2016). "In a first step, we identified 18 genetic variants none of them, with the exception of FLT3, previously known to be mutated in leukemia." (PMID 26886259, 2016). "Here we demonstrate that targeting TOPK expression or kinase activity results in suppression of FLT3 expression and inhibition of CEBPA phosphorylation leading to enhanced myeloid differentiation and remarkable in vitro and in vivo anti-leukemia activity, particularly in FLT3-ITD AML." (PMID 26450903, 2015).
leukemia (continued). "Such distinct addiction correlations may imply multitargeting opportunities for treating FLT3-ITD-driven leukemia, which currently lacks effective targeted treatment options." (PMID 26438695, 2015). "Therefore, we sought to investigate the biologic effect of TALEN-mediated FLT3 haplo-insufficiency on leukemia cell proliferation in vitro." (PMID 26669855, 2015). "Interestingly, we demonstrated that the TOPK inhibitor provides potent anti-leukemia activity, even in primary blasts with the FLT3-ITD mutation obtained from patients with AML who progressed after treatment with a potent FLT3 inhibitor (quizartinib, AC220)." (PMID 26450903, 2015). "Indeed, emerging small molecule inhibitor compounds have been shown to interfere with the aberrant FLT3 TK activity and lead to arrest of leukemia growth." (PMID 26450903, 2015). "To investigate whether the target addiction scoring can also reveal co-addiction relationships between drug targets, we correlated the addiction profile of FLT3-ITD with all of the other kinase targets across the 151 leukemia patient samples." (PMID 26438695, 2015). "In contrast, they displayed no inhibitory effects on MV-4-11 leukemia cells which carry a FLT3-ITD mutation." (PMID 25036984, 2014). "Mice injected with these transformed cell lines rapidly developed a leukemia-like illness, but transplantation of primary BM cells retrovirally transduced with FLT3-ITD causes only a myeloproliferative disease (MPD) and not leukemia." (PMID 25295230, 2014). "Consistent with the other mouse model, STAT5 was significantly more phosphorylated in FLT3-ITD mice compared to FLT3-D835Y mice, suggesting that differential STAT5 signaling may explain the different phenotypes seen between FLT3-TKD and FLT3-ITD leukemia." (PMID 25295230, 2014). "In the discussion of driver and passenger role for FLT3-ITD, it is difficult to neglect the possibility that leukemia with FLT3-ITD may be created through a fundamental genomic instability." (PMID 26237612, 2014). "Arguably, the most clinically relevant role of FLT3-TKD mutations in leukemia is the development of a secondary point mutation detected at relapse, as a mechanism of resistance in patients with a pre-existing ITD mutation and after FLT3 inhibitor therapy." (PMID 25295230, 2014). "The multi-kinase inhibitor sorafenib was initially evaluated in the COG Phase 1 trial ADVL0413 in children with advanced solid tumors and leukemias; two children with relapsed/refractory FLT3-ITD AML achieved ≥CR2 with sorafenib monotherapy on this trial and subsequently underwent HSCT." (PMID 24672775, 2014). "Importantly, subsequent studies of infant ALL patients revealed a worse overall prognosis with high levels of FLT3 expression in MLL-r leukemia." (PMID 25295230, 2014). "In CBF AML, which is frequently dependent upon KIT-mediated (gain-of-function) signal transduction, quizartinib demonstrated varying antiproliferative and cytotoxic efficacy in in vitro and ex vivo leukemia cells – in some cases within the low nanomolar range of FLT3 ITD (JM) positive samples." (PMID 23497317, 2013). "To explore whether Flt3 signaling in leukemia cells is important ex vivo, we studied the sensitivity of cultured primary MLL-ENL leukemia blasts to the FLT3 inhibitor PKC412." (PMID 23977266, 2013). "The selective upregulation of FLT3 in MLL-rearranged ALLs raised the possibility that FLT3 inhibitors could also be beneficial in the treatment of these aggressive leukemias." (PMID 23977266, 2013). "Therefore, investigating compounds that can inhibit both mutant and overexpressed wild type FLT3 in AML leukemia is warranted." (PMID 23497456, 2013). "Indeed, type I mutations are common in NUP98 rearranged leukemia, including mutations in the NRAS, KRAS, KIT, WT1 and FLT3 genes." (PMID 23332017, 2013).
leukemia (continued). "Furthermore, following transplantation of two of the primary Flt3+/+MLL-ENL leukemias, propagation of leukemia cells in the recipient mice was accompanied by a reduction in Flt3 protein levels." (PMID 23977266, 2013). "Previously, FLT3 mAb treatment was demonstrated to have efficacy in an FLT3 leukaemia mouse model." (PMID 23929599, 2013). "Kinase inhibition of (mutant) KIT, PDGFR and FLT3 isoforms by quizartinib leads to potent inhibition of cellular proliferation and induction of apoptosis in in vitro leukemia models as well as in native leukemia blasts treated ex vivo." (PMID 23497317, 2013). "Interestingly a spontaneous reduction of Flt3 expression upon transplantation of leukemia cells to secondary recipient mice was seen with two independent primary MLL-ENL leukemias." (PMID 23977266, 2013). "We showed that silvestrol is a compound with a potent anti-leukemia activity in FLT3-driven AML." (PMID 23497456, 2013). "Moreover, following transplantation into recipient mice, Flt3-null cells induce similar leukemias to their Flt3 wild type counterparts, providing evidence that Flt3 is dispensable to the genesis of leukemias induced by MLL-ENL or MLL-CBP." (PMID 23977266, 2013). "However, if the double knock-in is developed starting from MLL-PTD heterozygous and FLT3-ITD homozygous, the time of latency for leukemia development is markedly decreased, thus highlighting the importance of the FLT3-ITD dosage." (PMID 23936658, 2013). "The receptor tyrosine kinase FLT3 is highly expressed in these leukemias." (PMID 23977266, 2013). "Altogether, our findings suggest that Flt3 requirements may differ for survival of MLL-rearranged leukemia cells in vitro and leukemogenesis in vivo." (PMID 23977266, 2013). "In addition, treating newly diagnosed versus relapsed FLT3 ITD-positive leukemia native patient samples, a higher sensitivity profile for relapsed AML was verified." (PMID 23497317, 2013). "To explore whether the toxicity of PKC412 towards MLL-ENL leukemia cells was solely mediated by Flt3 inhibition, we studied the sensitivity of Flt3−/−MLL-ENL leukemias." (PMID 23977266, 2013). "Importantly, SOCS1 cooperated with FLT3-ITD in murine leukemia models in inducing a myeloproliferative disease." (PMID 23936658, 2013). "Flt3 level was inversely related to N-CoR status in various leukemia cells." (PMID 22514634, 2012). "We suspected that alteration of small non-coding microRNA (miRNA) expression in these leukemia cells is involved in the transformation process and used miRNA microarrays to determine the miRNA signature from total RNA harvested from FLT3/ITD expressing FDC-P1 cells (FD-FLT3/ITD)." (PMID 22970245, 2012). "Furthermore, using stable isotope labeling by amino acids in cell culture (SILAC), we were able to quantified over 400 phosphorylation sites (pTyr, pSer, and pThr) that were responsive to FLT3 inhibition in FLT3 driven human leukemia cell lines." (PMID 21552520, 2011). "These initial data suggested that the GL-1 cell line could be a relevant in vitro model for FLT3 activation, and if so, that canine leukemia models could be of use in the development of targeted FLT3 inhibitors." (PMID 21272320, 2011). "It provides a valuable resource for investigation of oncogenic FLT3 signaling in human leukemia." (PMID 21552520, 2011). "In this study, we identified five FLT3 tyrosine phosphorylation sites in primary leukemia cell lines, adding new information on how phosphorylation may affect the activity of wild-type FLT3 and FLT3-ITD." (PMID 21552520, 2011). "Similar to our results, LOH of dog chromosome 25 q was not seen in this small number of clinical leukemia samples, therefore, loss of wild-type FLT3 is not common in clinical specimens." (PMID 21272320, 2011).
leukemia (continued). "To find out a subset of phosphorylated proteins and their respective sites that are regulated by FLT3, we employed stable isotope labeling with amino acids in cell culture (SILAC) to differentially label proteins derived from FLT3 inhibited versus uninhibited leukemia cell lines." (PMID 21552520, 2011). "Consequently, combination therapy with an FLT3 inhibitor and an Hsp90 inhibitor, 17-AAG, was found to be effective against FLT3-ITD leukemia cells." (PMID 21453545, 2011). "In conclusion, FLT3 mutations are not common in our California childhood leukemia population, where RAS mutations are far more common." (PMID 20875128, 2010). "These regions of UPD seemed to be non-random and may be used to unmask pre-existing recessive mutations in leukemia genes, such as CEBPA, WT1, FLT3 and RUNX1." (PMID 18221515, 2008). "Thus, FLT3 expression was associated with HOXA5, HOXA7, HOXA9 and MEIS1 in human leukemia and this gene expression profile was confined to leukemia with either intermediate or unfavorable cytogenetics." (PMID 17712416, 2007). "Human primary AML cells (patient 1) were irradiated and examined for Flt3 and Hdm2 modulation, indicating that the reciprocal Flt3-Hdm2 response to DNA damage also could be present in primary leukemia cells." (PMID 17498302, 2007). "Additionally, dual inhibitors that target both JAK2 and other signaling molecules implicated in leukemia, such as FLT3, BCR-ABL, or RAS, may provide a more comprehensive therapeutic approach for patients with relapsed or refractory leukemia." (PMID 40486651, 2025). "Therefore, our data suggests that targeting the oncogenic activation of FLT3/SREBP/FASN axis may be a more effective strategy to enhance the anti-leukemia effect of quizartinib." (PMID 40263296, 2025). "Notably, such DNMT3A-mutated pre-leukemic cells were found in patients whose bulk leukemia cells also carried NPM1 and FLT3-ITD mutations, implying DNMT3A lesions arose earlier and persisted after the transient remission of the NPM1/FLT3-ITD-mutant leukemic clone." (PMID 40651916, 2025). "Similarly, in AML cells, glutaminolysis may represent a therapeutic vulnerability when paired with specific tyrosine kinase inhibitors in FLT3-ITD-driven leukaemia." (PMID 39795903, 2024). "Indeed, studies analysing drug responsiveness in ZNF384- and MLL/KMT2A-childhood ALL, suggested that FLT3 targeting therapy could be considered in these forms of leukaemia, especially in ZNF384-ALL." (PMID 38049555, 2024). "FLT3 inhibitors such as midostaurin and gilteritinib target FLT3 mutations seen in AML, while JAK2 inhibitors such as ruxolitinib inhibit JAK2, which may be activated in KMT2A‐r leukemia." (PMID 39428967, 2024). "Since leukemia cells harboring FLT3-ITD mutations are more sensitive to 2-DG treatment than wild-type cells, 2-DG may serve as a promising therapeutic target for AML patients with mutated FLT3." (PMID 38915288, 2024). "Interestingly, the hematopoietic cell kinase, normally expressed in the lymphoid and myeloid lineages of hemopoiesis, has been found to be enriched in dormant leukemia cells, interfering with the maturation of the FMS-like tyrosine kinase 3 (Flt3) and causing abnormal Flt3 signaling." (PMID 39301024, 2024). "In this work, we show that inhibiting MIF induces the death of leukemia cell lines and primary blasts and reprograms M2-like MΦ orientation when combined with GM-CSF, leading to blast cell death and reversal of resistance to therapies targeting FLT3-ITD or BCL-2 in vitro." (PMID 38548753, 2024). "Consequently, compound 11, as a strong and specific FLT3 hampering agent, could circumvent FLT3-ITD- leukemia cell lines." (PMID 37438819, 2023). "The two patients with dismal outcomes had already had significant risk factors at the time of the diagnosis of pregnancy‐associated leukemia: an FLT3‐ITD mutation in the AML patient and relapsed Ph‐negative ALL, both of which are known to confer a poor prognosis among adult patients." (PMID 37206296, 2023).